FGF23 (fibroblast growth factor 23)
Diseases named in the same sentence as FGF23 in open-access papers (continued):
Sharing a sentence is not in itself a finding about the gene and the disease.
cancer (55 papers, 2011 to 2026). A tumor composed of atypical neoplastic, often pleomorphic cells that invade other tissues. "The aim of this study was to investigate the impact of childhood cancer treatment on the levels of α-Klotho and FGF23 and to assess their potential associations with renal and cardiovascular function in children several years after anticancer treatment." (PMID 38792509, 2024). "Different types of cancers have altered expression and activities of genes encoding vitamin D metabolizing enzymes or vitamin D modulators such as Fibroblast growth factor-23 (FGF23)." (PMID 28300755, 2017). "ppGalNAc-T3 serves as an important test case as it is implicated in at least two medically important pathways: cancer metastasis and stabilization of FGF23." (PMID 28362263, 2017). "Therefore, the primary objective of the study was to determine if FGF23 impacts the prognosis of cancer patients with bone metastases, by testing the association between FGF23 serum levels with overall survival (OS)." (PMID 30736285, 2019). "The increase in total PLCγ expression has been shown in other inflammatory associated complications, including cancer and skin conditions that may be associated with altered FGF23 levels and is consistent with our findings." (PMID 30538676, 2018). "We next examined the impact of exogenous FGF23 on cellular phenotypes associated with cancer progression by adding exogenous FGF23 to LNCaP or PC3 PCa cells and measuring proliferation, invasion and soft agar colony formation relative to vehicle control treated cells." (PMID 26019137, 2015). "Beyond its classical endocrine actions on the kidney, accumulating evidence indicates that FGF23 exerts broad paracrine and systemic effects that extend to metabolism, inflammation, cardiovascular function and cancer biology." (PMID 41833603, 2026). "Some patients received anti-cancer therapies, including doxorubicin (inhibiting DNA/RNA synthesis), burosumab (a monoclonal antibody targeting FGF-23), or infigratinib (an FGF receptor inhibitor)." (PMID 41182108, 2025). "As previously noted, FGF23 downregulates serum Pi by increasing urinary Pi excretion in the kidneys, and levels of FGF23 are elevated in many cancers." (PMID 40643473, 2025). "The existing literature highlights a gap in understanding the involvement of FGF23 and α-Klotho in pediatric cancer patients." (PMID 38792509, 2024). "The available literature lacks data on the role of α-Klotho and FGF23 in children treated for cancer." (PMID 38792509, 2024). "The results of our study revealed that FGF6, FGF20, FGF22, and FGF23 are crucial biomarker proteins that NSP-B specifically targets for the therapy of cancer." (PMID 38434705, 2024). "FGF23 is particularly important for those forms of cancer that primarily affect bone and/or are characterized by bone metastasis." (PMID 36926025, 2023). "For this purpose, the FGF23 concentrations were measured in blood plasma samples of healthy subjects and cancer patients using both the SPRI biosensor and the ELISA." (PMID 37895007, 2023). "The biomarkers most significantly associated with short-term mortality were IL-6, IL-10, IL-8, MCP-1 (mainly inflammatory markers), FGF-21, ST1A1, 4E-BP1 and CST5 (classified by OLINK as cardiovascular markers) and FGF-23 (classified as a cancer marker)." (PMID 36209229, 2022). "FGF23 signaling contributes to regulation in cellular proliferation, survival, and differentiation making it an attractive pathway to hijack by cancer cells." (PMID 33191899, 2021). "Clearly, this and the role of FGF23-dependent phosphate metabolism in cancer require further studies." (PMID 33520985, 2020). "Sclerostin, DKK-1, and FGF23 are osteocyte-specific markers; they were studied to evaluate their contribution to osteocyte/cancer cell crosstalk." (PMID 32640686, 2020).
cancer (continued). "Definitely, further research on pathological derangements of phosphate homeostasis is warranted to uncover the relationship between FGF23/KL dysregulation, disturbed phosphate homeostasis, and cancer development." (PMID 33520985, 2020). "In this study, the authors aimed to assess the impact of serum FGF23 levels in the prognosis of patients with cancer and bone metastases from solid tumors." (PMID 30736285, 2019). "Evaluating the contribution of osteocyte-specific markers – FGF23, sclerostin, Dkk-1 – is important, as these proteins have gained attention as potential targets in cancer treatments." (PMID 30568232, 2018). "Using this model we showed, for the first time to the best of our knowledge, that the expression of osteocytic FGF23, an emerging drug target in cancer and other ailments, increased significantly in the presence of PCa cells." (PMID 30568232, 2018). "Even less is known on the role of circulating levels of FGF21, FGF19 or FGF23 as a cancer biomarker." (PMID 27358750, 2016). "FGF23 mRNA was detected in both benign and cancer tissues, with 3.6-fold higher levels in the cancer tissues (p<.001, t-test)." (PMID 26019137, 2015). "While there have been a number of studies related to vitamin D and cancer endpoints, few have investigated the potential role of FGF-23 in this pathway." (PMID 21383962, 2011). "In those forms of cancer that involve or originate from bone, FGF23 signaling may directly contribute to cancer biology and/or progression." (PMID 36926025, 2023). "In vitro, FGF-23 is overexpressed in osteoblast-like cells exposed to chemotherapeutics, while it has been established that FGF-23 may be upregulated in some cancers." (PMID 35269781, 2022). "In the present study, the authors hypothesize that high levels of circulating FGF23 could negatively contribute to the prognosis of cancer patients with bone metastases, due to FGF23’s ability to promote cancer progression." (PMID 30736285, 2019). "Further clinical and observational studies exploring the potential roles of calcium and phosphate in cancer should take into account their regulators such as vitamin D, parathyroid hormone, and fibroblast growth factor 23 (FGF-23) in order to fully comprehend how they are involved in carcinogenesis." (PMID 26284119, 2015). "Moreover, also FGF23 and phosphate have been revealed to be factors relevant in cancer." (PMID 33520985, 2020). "Thus, a drug or molecule that blocks ppGalNAc-T3 could be used to lower FGF23 levels in patients with kidney disease and potentially prevent cancer cells from spreading." (PMID 28362263, 2017). "FGF-23 is a representative of the fibroblast growth factor family and is classified by OLINK as a cancer marker." (PMID 37600039, 2023). "Interestingly, other researchers suggested that FGF23 may play a role in cancer." (PMID 32640686, 2020). "Finally, they also have endocrinological functions, regulating the phosphate metabolism through fibroblast growth factor 23 (FGF23); more roles for osteocytes in cancer, and other pathologies are emerging constantly." (PMID 34206294, 2021). "FGFR signaling regulates the growth and progression of many cancers including MM, but a role for FGF23 in MM has not been reported." (PMID 25944690, 2015). "FGF23 and FGF6 have been reported as gained in CRC and other cancer types." (PMID 24367615, 2013). "Even though FGF19, FGF21 and FGF23 are all endocrine factors, based on the effects of FGF21 on fuel energy, oxidative stress, life-span and its pleiotropic metabolic actions; investigators have suggested that FGF21 is a very promising molecule with therapeutic potential to combat cancer." (PMID 27358750, 2016).
infection (32 papers, 2013 to 2025). The state of being infected such as from the introduction of a foreign agent such as serum, vaccine, antigenic substance or organism. "In patients with CKD, higher levels of FGF23 are associated with increased infection-related mortality and hospitalizations for infection." (PMID 38732094, 2024). "There is currently limited evidence concerning the potential mechanisms related to the association of high baseline FGF23 levels and increased risk of severe infections." (PMID 36828412, 2023). "Evidence regarding the potential mechanisms pertaining to the association of high FGF23 levels and increased risk of severe infection remains elusive." (PMID 37637614, 2023). "Increased FGF23 levels associate with higher infection-related hospitalizations and adverse infectious outcomes." (PMID 36828412, 2023). "In CKD patients, high serum FGF23 has been independently correlated with an increased risk of infection, resulting in hospitalisation and increased mortality." (PMID 36829583, 2023). "Recent clinical association studies suggest that elevated FGF-23 contributes to an increase in susceptibility or severity of infections in CKD." (PMID 29946298, 2018). "Similar to intact FGF23, high C-terminal FGF23 is associated with worse clinical outcomes and increased mortality and has been associated with increased rates of severe infections." (PMID 36828412, 2023). "Recently, FGF23 has been associated with a higher proportion of infections in ESRD patients." (PMID 30909513, 2019). "High FGF23 levels, whether pre or post inflammatory insult, may affect the regulation of the innate immune response, consequently causing poorer clearance of secondary infections and death." (PMID 36829583, 2023). "Administration of LPS to wild-type mice increases Fgf23 gene and protein expression as early as the hepatic expression of the inflammatory cytokines Tnf, Il6, and Il-1b and causes hypoferremia as an acute phase response to infection and inflammation aiming to reduce iron availability for pathogens." (PMID 33416083, 2021). "Our findings suggest that hepcidin increases while i-FGF23 decreases significantly in acute pediatric infections and that their fluctuations depend on the presence of infection." (PMID 39336155, 2024). "In this study, i-FGF23 was significantly positively correlated for the first time with Fe and TS in acute pediatric infections, whereas the correlations of hepcidin with iron-related parameters were proven to be stronger." (PMID 39336155, 2024). "Experimental studies suggest a direct pro-inflammatory effect of FGF23 on macrophages, which is key to the innate immune response to infection/inflammation." (PMID 36829583, 2023). "The Hemodialysis (HEMO) research found that greater FGF23 levels were significantly related with infection death." (PMID 37636568, 2023). "PTH is modulated by FGF23, and low PTH levels have been associated with increased infection rates in ESRD patients." (PMID 36828412, 2023). "In the long-term post-infection group, however, we observed a significant increase in FGF23 expression, which was further exacerbated by treatment with SPK (5 mg/kg)." (PMID 37626956, 2023). "FGF23 signaling also impairs leukocyte recruitment in vitro and in vivo during CKD, and the disordered leukocyte recruitment increased predisposition to infections by weakening host response." (PMID 35966090, 2022). "In conclusion, we identified a group of cytokines, including IL-17C, MMP-10, FGF-23, CCL23, FGF-19 and CXCL5 that are differentially regulated during asymptomatic and mild symptomatic infections and are known to be associated with tissue repair functions." (PMID 35479098, 2022). "An in vitro study revealed that fibroblast growth factor 23 (FGF23), which is elevated in response to phosphate load, impaired leukocyte recruitment and was associated with an increased risk of infection-related hospitalization." (PMID 32286455, 2020).
infection (continued). "The authors proposed that elevated circulating levels of FGF-23 directly activated FGFR2 in PMNs to impair the host response to infection." (PMID 29946298, 2018). "In this scenario, infection with bacteria stimulates the production of FGF-23 locally in M1 activated macrophages which also upregulate FGFR/α-Kl complexes." (PMID 29946298, 2018). "In terms of infection risk, if the function of white blood cells is inhibited at low levels of both phosphorus and vitamin D, then the suggestion might be that kidney dysfunction and infection are more closely associated with Fibroblast Growth Factor 23 than with parathyroid hormone." (PMID 30134544, 2018). "Inflammation increases circulating FGF-23 levels in both animal models and humans in response to infection, inflammation, and oxidative stress." (PMID 29946298, 2018). "The serum levels of FGF‐23 are upregulated by inflammation, infection and oxidative stress." (PMID 39754578, 2025). "Median hepcidin was significantly elevated in both infection groups compared to controls, with the highest value recorded in patients with bacterial infections (56.9 ng/mL, p < 0.001), whereas median i-FGF23 was similarly reduced in both infection groups compared to controls (p < 0.001)." (PMID 39336155, 2024). "It has been shown that elevated FGF23 in mice with CKD impairs neutrophil recruitment and disrupts the host defense mechanism in infection, whereas neutralization of FGF23 restores neutrophil recruitment and protects the host against pathogens during infection." (PMID 39666728, 2024). "Hepcidin levels increase, whereas i-FGF23 levels decrease in acute pediatric infections." (PMID 39336155, 2024). "FGF23 via prevention of β2-integrin activation inhibits the neutrophils' activation, binding, and migration and, thus, has been related to a higher prevalence of infections in ESRD patients." (PMID 37637614, 2023). "FGF23 is thought to impair the host’s response to infection and the innate immune response." (PMID 36831276, 2023). "Besides, FGF23 indirectly increases inflammation and infection by suppressing vitamin D production in the kidney’s proximal tubule." (PMID 36012420, 2022). "As a result, a higher FGF-23 concentration is associated with increased infection risk in patients irrespective of kidney disease." (PMID 36012420, 2022). "Taken together, in various cohorts, associations between FGF23 and CVD or inflammation were found, but if lowering FGF23 in CKD could reduce the FGF23-associated all-cause, cardiovascular mortality or risk for infection is unknown." (PMID 33416083, 2021). "Another potential explanation for the association between serum albumin-corrected calcium level and infection-related death may be calcium-induced increases in circulating FGF23 and calciprotein particles (CPPs)." (PMID 32286455, 2020). "Furthermore, clinical studies showed that fibroblast growth factor 23 (FGF23), which increases in response to P loading, was closely associated with serum inflammatory markers and an increased risk of infection-related hospitalization in hemodialysis patients." (PMID 30061632, 2018). "Based on these findings, a new hypothesis proposes that FGF-23 actions on innate immunity are mediated by activation of reconstituted canonical FGFR/α-Kl receptors in tissue macrophages during infections by both systemic and local production of FGF-23." (PMID 29946298, 2018). "However, in patients with CKD with hemodialysis, high FGF23 is not the cause of infection or systemic inflammation but is positively associated with vascular calcification (VC)." (PMID 35966090, 2022). "In particular, we found increased TGF-β1, FGF23, NGAL, IL-18, HIF1-α, TLR2, YKL-40, and B2M mRNA levels long-term post MHV-1 infection." (PMID 37626956, 2023). "Interestingly, PA infection caused a significant downregulation of TGFβ and α-klotho expression—a key CF modifier gene and FGF23 co-receptor, respectively—which were also not altered by FGF23 treatment." (PMID 37763754, 2023).
infection (continued). "In conclusion, a new understanding of FGF-23 functions proposes functions beyond mineral metabolism that includes indirect and direct effects on components of the myeloid lineage that may account for the association between elevated FGF-23 and impaired host responses to infections." (PMID 29946298, 2018). "Fibroblast growth factor (FGF)-23, TFRC, FGFR4, and ATPase H+ transporting V0 subunit B (ATP6V0B) were the upregulated genes identified in A. baumannii without resistant gene infection-associated pulmonary host responses." (PMID 39857726, 2025). "Ultimately, it seems that infection with PA does not involve FGF23/FGFR signaling and independently activates PLCγ in the CF bronchial epithelium." (PMID 37763754, 2023). "Regarding the mRNA expression, a significant increase in TGF-β1, HIF-1α, NGAL, B2M, FGF23, TLR-2, IL-18, and YKL-40 was observed in the long-term post-MHV-1 infection, whereas only NGAL was found to be significantly increased in the acute stage post-infection." (PMID 37626956, 2023). "Independently from klotho, the increased FGF23 effect on FGFR-2 on neutrophils inactivates b2-integrin and prevents neutrophil recruitment to infection sites, which may help to partially explain the compromised host defense brought on by neutrophil dysfunction in CKD patients." (PMID 36831276, 2023). "In addition, a post hoc analysis of the Cardiovascular Health Study (CHS study) in community-dwelling adults over 65 years (with or without CKD) found that those with high FGF23 levels had a higher rate of first infection-related hospitalization." (PMID 36828412, 2023). "Moreover, WT mice were infected with mouse FGF23 promoter WT-luciferase (Ad-FGF23 WT-luc) or ERRE mutant-luciferase (Ad-FGF23 mut-luc) constructs via tail vein injection, and treated with vehicle or ethanol intragastically for 12 h after four days of infection." (PMID 38479224, 2024).
genetic disorders (30 papers, 2012 to 2025). "Tumoral calcinosis is an extremely rare genetic disease caused by mutations in three genes, GALNT3, FGF23, and KL, which disrupt phosphorus metabolism." (PMID 38792634, 2024). "Recent studies of human genetic disorders and genetically engineered mice, as well as the in vitro approaches, have proved that FGF-23 overexpression not only suppresses osteoblastic proliferation but also impairs bone mineralization." (PMID 32517762, 2020). "Impaired skeletal development is one major feature found in genetic disorders attributed to FGF23 overexpression." (PMID 30374308, 2018). "Human genetic diseases and mouse experiments have conclusively shown that both gain andloss of function of FGF23 primarily targets the kidney." (PMID 29096595, 2017). "Although genetic disease is associated with disturbed FGF23 homeostasis, the plasma levels of FGF23 do not reach the extreme levels as seen in CKD patients." (PMID 33233840, 2020).